POLR1C (RNA polymerase I and III subunit C)
Description:
DNA-dependent RNA polymerase catalyzes the transcription of DNA into RNA using the four ribonucleoside triphosphates as substrates. Common component of RNA polymerases I and III which synthesize ribosomal RNA precursors and short non-coding RNAs including 5S rRNA, snRNAs, tRNAs and miRNAs, respectively. POLR1C/RPAC1 is part of the polymerase core and may function as a clamp element that moves to open and close the cleft.
Synonyms: RPA40; RPA39; RPA5; RPAC1; AC40; RPC40; HLD11; TCS3
Tractability: Small molecule: a structure with a bound ligand is known. PROTAC: ubiquitination databases record sites on it; its protein half-life has been measured.
Gene: Protein-coding gene on chromosome 6 (43,509,702 to 43,562,419, forward strand). Ensembl gene ENSG00000171453.
Subcellular location: Nucleus; Nucleus, nucleolus; Cytoplasm, cytosol
Subcellular location (Human Protein Atlas): Nucleoli fibrillar center; Nucleoplasm
Pathways (Reactome):
Gene expression (Transcription): B-WICH complex positively regulates rRNA expression; NoRC negatively regulates rRNA expression; RNA Polymerase I Promoter Escape; RNA Polymerase I Transcription Initiation; RNA Polymerase I Transcription Termination; RNA Polymerase III Abortive And Retractive Initiation; RNA Polymerase III Chain Elongation; RNA Polymerase III Transcription Initiation From Type 1 Promoter; RNA Polymerase III Transcription Initiation From Type 2 Promoter; RNA Polymerase III Transcription Initiation From Type 3 Promoter; RNA Polymerase III Transcription Termination
Immune System: Cytosolic sensors of pathogen-associated DNA
Gene Ontology:
Molecular function: protein binding; DNA-directed RNA polymerase activity; DNA binding; protein dimerization activity
Biological process: termination of RNA polymerase III transcription; transcription by RNA polymerase III; transcription elongation by RNA polymerase I; transcription initiation at RNA polymerase III promoter; nucleolar large rRNA transcription by RNA polymerase I; termination of RNA polymerase I transcription; transcription by RNA polymerase I; transcription initiation at RNA polymerase I promoter; DNA-templated transcription
Cellular component: cytoplasm; fibrillar center; nucleoplasm; nucleus; RNA polymerase I complex; RNA polymerase III complex; cytosol; nucleolus
Genetic constraint (gnomAD): Loss-of-function variants: 36 observed, 37.7 expected, observed/expected ratio (o/e) 0.95, 90% interval 0.73 to 1.26. The upper end of that interval is the gene's LOEUF score, 1.26, which puts it in group 5 of 6, group 1 being the genes least tolerant of losing a copy. Missense variants: 495 observed, 461.77 expected, observed/expected ratio (o/e) 1.07, 90% interval 1 to 1.15. Synonymous variants: 161 observed, 170.26 expected, observed/expected ratio (o/e) 0.95, 90% interval 0.83 to 1.08.
Gene-disease validity (ClinGen):
ClinGen rates the evidence that POLR1C causes each of these diseases.
POLR1C-related disorder (autosomal recessive): Definitive. Disorder in which the cause of disease is a variation in the POLR1C gene.
Treacher Collins syndrome 3 (autosomal recessive): Moderate. Any Treacher-Collins syndrome in which the cause of the disease is a mutation in the POLR1C gene.
Homologues: Orthologues: chimpanzee POLR1C (100% identical), macaque POLR1C (99% identical), dog POLR1C (97% identical), guinea pig POLR1C (97% identical), pig POLR1C (97% identical), rabbit POLR1C (97% identical), rat Polr1c (95% identical), mouse Polr1c (94% identical), zebrafish polr1c (72% identical), tropical clawed frog polr1c (71% identical), Drosophila melanogaster Polr1C (51% identical), Caenorhabditis elegans rpac-40 (48% identical). Paralogues in human: POLR2C (27% identical), CRIPT (8% identical).